H19 (H19 imprinted maternally expressed transcript)
Diseases named in the same sentence as H19 in open-access papers (continued):
Sharing a sentence is not in itself a finding about the gene and the disease.
pulmonary fibrosis (21 papers, 2016 to 2025). Chronic progressive interstitial lung disorder characterized by the replacement of the lung tissue by connective tissue, leading to progressive dyspnea, respiratory failure, or right heart failure. "The interaction between H19 and miR-29b is implicated in bleomycin-induced idiopathic pulmonary fibrosis, and miR-29b has been revealed to function as an oncomir in oral cancer." (PMID 33672311, 2021). "In vivo studies further revealed H19 deficiency significantly reduced bleomycin-induced pulmonary fibrosis." (PMID 33138822, 2020). "H19 deficiency ameliorated bleomycin-induced pulmonary fibrosis and repressed the activation of TGF-β/Smad and S1pr2/Sphk2 in the lungs of bleomycin-treated mice." (PMID 33138822, 2020). "We further determined the functional roles and underlying mechanisms of H19 in pulmonary fibrosis, which suggested H19 acts as a profibrotic lncRNA in the lungs." (PMID 33138822, 2020). "In addition to COL1A1, H19 is also positively associated with α-SMA (ACTA2) expression in bleomycin-induced lung fibrosis." (PMID 33672311, 2021). "Studies have shown that lncRNA H19 promotes bleomycin-(BLM) induced pulmonary fibrosis by regulating the miR-196a/COL1A1 pathway." (PMID 36478088, 2023). "The involvement of miRNAs has been confirmed in pulmonary fibrosis, and H19 has been shown to bind the 3′UTR and inhibit the expression of the fibrosis regulator, miR-29b." (PMID 36188624, 2022). "For example, H19 promotes pulmonary fibrosis by inhibiting the expression of miR-140 in human lung fibroblasts (HFL), leading to enhanced deposition of extracellular matrix." (PMID 36188624, 2022). "Upregulated lncRNA H19 in tissues from IPF patients downregulates miR-140 and modulates TGF-β/Smad3 signaling, and further in vivo and in vitro experiments show that the knockdown of H19 diminishes pulmonary fibrosis." (PMID 34819948, 2021). "Several studies have shown that H19 is highly upregulated in pulmonary fibrosis in vivo and in vitro." (PMID 33533071, 2021). "Nonetheless, H19 seems to promote other fibrotic conditions, such as pulmonary fibrosis, cardiac fibrosis, or cholestatic liver fibrosis." (PMID 33672311, 2021). "H19 exhibited promotive effect on bleomycin (BLM)-induced idiopathic pulmonary fibrosis (IPF) via interacting with miR-29b." (PMID 32812641, 2020). "H19 knockout ameliorated bleomycin-induced pulmonary fibrosis through attenuating the TGF-β/Smad and S1pr2/Sphk2 pathways." (PMID 33138822, 2020). "According to the previous studies, lncRNA H19 promotes lung fibrosis through lncRNA H19-miR-197a and lncRNA H19-miR-29b interactions." (PMID 33193637, 2020). "The Masson’s Trichrome staining and Sirius red staining further indicated that 4-week BLM significantly induced lung fibrosis in WT mice, but had much less impact in H19−/− mice." (PMID 33138822, 2020). "Consistently, quantitation of lung fibrosis in a blinded manner revealed the Ashcroft score decreased significantly in H19−/− BLM mice when compared to Wt BLM mice." (PMID 33138822, 2020). "The expression of lncRNA H19 is significantly up-regulated in idiopathic pulmonary fibrosis in a bleomycin-(BLM) induced lung fibrosis model and leads to ECM deposition in vivo and in vitro." (PMID 30287731, 2018). "Additionally, the therapeutic usage of H19 in pulmonary fibrosis was highlighted where silencing of H19 enhanced the expression of the miR-140 which finally repressed TGF-β1." (PMID 39912974, 2025). "The miR-196a/COL1A1 axis is known to be regulated by lncRNA H19 in pulmonary fibrosis." (PMID 33511215, 2021). "Finally, in vitro and in vivo results have shown that downregulation of H19 attenuates lung fibroblast activation and pulmonary fibrosis, the phenomenon that can be reversed by miR-196a inhibitors." (PMID 33817326, 2021). "H19 downregulation alleviates fibroblast activation and lung fibrosis." (PMID 33533071, 2021).
pulmonary fibrosis (continued). "In present study, we identified H19 as an up-regulated lncRNA in the lungs of pulmonary fibrosis." (PMID 33138822, 2020). "We thus propose that H19 contribute to lung fibrosis of IPF may via regulating both TGF-β/smad and S1pr2/SphK2 signalling." (PMID 33138822, 2020). "Although these studies suggest a causal link among H19 and pulmonary injury, it remains unknown whether and to what extent H19 is involved in the regulation of pulmonary fibrosis in vivo." (PMID 33138822, 2020). "Moreover, lncRNA H19 knockdown could reduce the progression of pulmonary fibrosis via the lncRNA H19-miR-140-TGF-β/Smad3 regulatory network, suggesting that lncRNA H19 may serve as an early diagnostic and prognostic biomarker for pulmonary fibrosis." (PMID 35289324, 2022). "In addition to, H19 expression increased upon bleomycin-induced lung fibrosis in rats." (PMID 33138822, 2020). "Similarly, H19 mRNA also increased in a model of bleomycin-induced pulmonary fibrosis." (PMID 33138822, 2020). "Furthermore, H19 was also related to progression of lung cancer and lung fibrosis." (PMID 33138822, 2020). "Through competition with miR-196a, H19 participates in the regulation of COL1A1, thereby mediating pulmonary fibrosis." (PMID 39944354, 2024). "They found that the expression of H19 was significantly increased in TGF-β-induced fibroblasts and BML-induced pulmonary fibrosis." (PMID 33817326, 2021). "In addition, down-regulated H19 expression could inhibit fibroblast activation and lung fibrosis." (PMID 30458806, 2018). "Currently, we have not found drugs that can target H19 to treat diseases such as pulmonary fibrosis, asthma and pneumonia." (PMID 36188624, 2022). "The pathogenesis of asthma and pneumonia are all related to the production of inflammation, and pulmonary fibrosis is related to the production of fibrosis, and H19 is highly expressed in these diseases without exception." (PMID 36188624, 2022). "This confirmed once again that lncRNA H19 could promote the expression of COL1A1 through the competitive binding of microRNA-196a and accelerate the process of pulmonary fibrosis." (PMID 33817326, 2021). "Similarly, H19 is a direct target of COL1A1 expression by sponging miR196a or miR‐29b in TGFβ‐induced fibroblast proliferation and bleomycin‐induced lung fibrosis." (PMID 33533071, 2021). "H19 is upregulated via diminishing miR‐140 expression in fibrotic tissues from IPF patients and bleomycin‐induced pulmonary fibrosis in mice and TGFβ1‐induced HBE and A549 cells, in which the TGFβ/Smad3 signal pathway is involved in myofibroblast generation and extracellular matrix deposition." (PMID 33533071, 2021).
multiple myeloma (20 papers, 2017 to 2025). "Interrestingly, several studies have been performed to explore the diagnostic value of lncRNA H19 in cancer detection and diagnosis: high H19 serum levels in patients with certain myeloma and nonsmall cell lung carcinoma have been suggested to be useful for diagnosis and prognosis." (PMID 33335214, 2020). "This includes specific resistance to the proteasome inhibitor bortezomib in multiple myeloma, which is driven by an N6-methyladenosine (m6A)-mediated upregulation of lncRNA H19, functioning as a sponge to regulate the miR-184/CARM1 axis." (PMID 41379397, 2025). "Many lncRNAs, such as MALAT1, GAS5, DLEU2, and H19, have been reported to be involved in the diagnosis and progression of multiple myeloma (MM)." (PMID 36607351, 2023). "Another study reported that blocking H19 along with reducing NF-κB expression blocked the growth of myeloma cells." (PMID 34421359, 2021). "The results showed that after knocking down H19, the proliferation and migration of myeloma cells were inhibited and cell apoptosis was enhanced markedly, whereas the expression level of miR-29b-3p and H19 in serum was opposite." (PMID 30728351, 2019). "On the basis of these previous findings, the present study was intended to explore the biological function of H19, interactions between the downstream target genes, and the effect of H19 on BTZ resistance of myeloma cells." (PMID 30728351, 2019). "We found that H19 promotes epithelial-mesenchymal transformation, and its knockdown can inhibit the growth of multiple myeloma cells through the NF-κB pathway, suggesting that H19 may play a role in the development of inflammatory diseases." (PMID 38895124, 2024). "A previous study showed that H19 was elevated in myeloma patients and cell lines." (PMID 34421359, 2021). "It was demonstrated in the present study that most H19 was located in the cytoplasm of myeloma cells, suggesting that H19 may regulate the process of drug resistance in MM via ceRNA." (PMID 30728351, 2019). "PCAT1, ANRIL, H19, ANGPTL1‐3, or NEAT1 upregulation induced myeloma cells insensitive to bortezomib, whereas CRNDE overexpression leads to dexamethasone tolerance." (PMID 36057947, 2023). "H19 is significantly upregulated in the bone marrow of MM patients, whereas lower H19 levels are observed in samples obtained from MGUS or smoldering multiple myeloma (SMM) patients." (PMID 37987364, 2023). "LncRNA H19 via sponging miR-152-3p up-regulates the expression of BRD4, thereby promoting the malignant behavior of multiple myeloma cells." (PMID 34324544, 2021).
osteoporosis (20 papers, 2020 to 2026). A condition of reduced bone mass, with decreased cortical thickness and a decrease in the number and size of the trabeculae of cancellous bone (but normal chemical composition), resulting in increased fracture incidence. "lncRNA H19 was upregulated in BMSCs from the osteoporosis group, whereas miR‐29b‐3p was downregulated." (PMID 38685675, 2024). "This study aimed to explore the molecular mechanism of long non‐coding RNA H19 in osteoporosis after SCI and provide new research directions for existing prevention strategies." (PMID 38685675, 2024). "We investigated the regulatory functions and mechanisms of miR‐29b‐3p and H19 in controlling osteogenic development of BMSCs during osteoporosis following SCI." (PMID 38685675, 2024). "Our findings suggest that long non‐coding RNA H19 mediates BMSCs' osteogenic differentiation in osteoporosis after SCI through the miR‐29b‐3p/DKK1 axis and by directly inhibiting the β‐catenin signalling pathway." (PMID 38685675, 2024). "Consistent with a previous study, we found that H19 was significantly upregulated in BMSCs in a rat model of osteoporosis after SCI." (PMID 38685675, 2024). "This study aimed to explore the molecular mechanism of H19 in osteoporosis after SCI and provide new research directions for existing prevention strategies." (PMID 38685675, 2024). "In conclusion, the pathophysiology of osteoporosis following SCI is significantly influenced by the H19/miR‐29b‐3p/DKK1 axis." (PMID 38685675, 2024). "Conversely, the downregulation of H19 ameliorated osteoporosis by promoting osteoblast differentiation and restraining osteoclast formation." (PMID 39156986, 2024). "Based on previous studies, several ubiquitous lncRNAs, including Malat1, H19, Hotair, MEG3 and Dancr, were previously reported to be associated with osteoporosis." (PMID 36983039, 2023). "Collectively, the findings presented in this study support H19 as a potential therapeutic target for osteoporosis and repair of fragility fractures through the modulation of the ECM components and the ECM-cell interactions." (PMID 36882843, 2023). "In this study, we aim to investigate the role of H19 in ECM composition using osteoporosis-derived MSCs and to determine the impact of H19-engineered matrices on naïve MSCs and pre-adipocytes behavior." (PMID 36882843, 2023). "LncRNA H19 is a pro-osteogenic molecule that has been found to be deregulated in osteoporosis, both in human patients and animal models." (PMID 36882843, 2023). "The prospect of targeting lncRNA H19 in the treatment of osteoporosis is promising because of the effects that lncRNA H19 has on the process of osteogenic differentiation." (PMID 34583640, 2021). "Bioinformatics analysis showed that DKK4 is the target gene of H19, and through the Wnt/β-catenin pathway to mediate the biological effects of H19 in disused osteoporosis." (PMID 34583640, 2021). "In this review, we summarize the molecular pathways and mechanisms of lncRNA H19 in the pathogenesis of osteoporosis and summarize the research progress of targeting H19 as a treatment option." (PMID 34583640, 2021). "Further research is needed into how H19 regulates osteogenic differentiation and how it participates in osteoporosis." (PMID 34583640, 2021). "Both H19 and miR675 are up-regulated in osteoporosis differentiation and miR-675 down-regulates TGF-β1." (PMID 34583640, 2021). "Some studies have shown that miR-29a-3p is the target of H19, and the expression of H19 is up-regulated in patients with osteoporosis." (PMID 34583640, 2021). "H19 expression is inhibited in patients with osteoporosis and bone defects, suggesting that H19 is a therapeutic target for these diseases." (PMID 34592982, 2021). "The significant decrease of H19 and increase expression of miR-19b-3p were found in postmenopausal osteoporosis patients." (PMID 34384352, 2021).
osteoporosis (continued). "Based on the effects of H19 on the process of osteogenic differentiation, the potential use of H19 in the treatment of osteoporosis can be studied." (PMID 34583640, 2021). "An in-depth understanding of the DNA methylation mechanism of H19 will provide a new direction for the treatment of osteoporosis." (PMID 34583640, 2021). "In the present study, we observed a significant decrease of H19 expression in postmenopausal osteoporosis patients and in BMP-2 induced BMSCs compared with controls, which was consistent with a former study." (PMID 31918667, 2020). "The results showed a significant decrease of H19 expression in postmenopausal osteoporosis patients compared to healthy controls." (PMID 31918667, 2020). "The expression of miR-19b-3p and lncRNA H19 were measured in postmenopausal osteoporosis patients and BMP-22 induced BMSCs using qRT-PCR." (PMID 31918667, 2020). "Many studies have indicated that H19 is involved in the occurrence and development of osteoporosis." (PMID 38685675, 2024). "A study showed the upregulation of H19 in patients with osteoporosis." (PMID 39156986, 2024). "Recent research has unveiled H19’s pivotal role in osteoporosis and bone tissue regeneration." (PMID 39156986, 2024). "The role of H19 in osteoporosis has been extensively studied." (PMID 38685675, 2024). "When treating osteoporosis, targeting H19 may have unintended consequences, such as interfering with regular cell functions that H19 regulates in other tissues." (PMID 39156986, 2024). "Furthermore, some contrasting results were reported for the H19 expression in postmenopausal osteoporosis patients." (PMID 37189829, 2023). "Data from previous studies confirmed a new signalling cascade in disuse osteoporosis (DOP): mechanical unloading causes the upregulation of DNMT1 and methylation of the H19 promoter, and ultimately leads to downregulation of H19 and inhibition of ERK signalling." (PMID 34498342, 2021). "In this review, we discuss the role of lncRNA H19 in osteogenic differentiation, and summarize the relevant mechanisms of action to provide a theoretical basis for exploring lncRNA as a new molecular target in the treatment of osteoporosis." (PMID 34583640, 2021). "According to the latest research, H19 is down-regulated in the plasma of postmenopausal patients with osteoporosis and can control osteogenic differentiation by targeting related factors to participate in osteoporosis." (PMID 34583640, 2021). "Since quercetin treatment increased H19 expression during quercetin-induced BMSCs osteogenic differentiation, quercetin may be used for the clinical treatment of osteoporosis and bone defects." (PMID 34592982, 2021). "Therefore, the H19/miR-29a-3p axis is also involved in the development of osteoporosis by regulating osteoclasts." (PMID 34583640, 2021). "H19 expression was determined in postmenopausal osteoporosis patients and healthy controls." (PMID 31918667, 2020). "In particular, the lncRNA H19 (H19) is a key regulator of osteoblast function, and is involved in the development of disuse osteoporosis, suggesting that lncRNAs may play a key role in unloading-induced bone loss." (PMID 32427900, 2020). "Therefore, we speculated that the H19‐miR‐29b‐3p‐DKK1 axis plays a crucial role in osteoporosis after SCI by regulating the differentiation of BMSCs." (PMID 38685675, 2024). "Furthermore, H19 is expressed at low levels in disuse osteoporosis." (PMID 36882843, 2023). "Furthermore, there are some studies on H19 in the blood of patients with osteoporosis." (PMID 34583640, 2021). "Thus, miR‐29b‐3p and H19 may serve as reliable indicators of osteoporosis." (PMID 38685675, 2024). "In the same samples, H19 expression shows an antagonistic profile, being upregulated in MSC derived from osteoporosis patients versus healthy donors." (PMID 36882843, 2023). "Several lncRNAs, including Malat1, H19, HOTAIR, MEG3 and DANCR, were largely involved in the osteoporosis." (PMID 36983039, 2023).
osteoporosis (continued). "However, the process of how lncRNA H19 modulates the pathogenesis of osteoporosis remains unclear." (PMID 34583640, 2021). "Therefore, while H19 offers promising avenues for therapeutic applications in osteoporosis and bone regeneration, its role remains complex and not fully delineated." (PMID 39156986, 2024). "We did not obtain a different H19 expression in patients who suffered from osteoporosis." (PMID 37189829, 2023). "In addition, studies have found that H19 mediates estrogen-regulated osteogenic differentiation in BMSCs through the miR-532-3p/SIRT1 axis, and estrogen can mediate miR-532-3p/SIRT1 axis to reduce osteoporosis in ovariectomy rats by up-regulating H19." (PMID 34583640, 2021). "In addition, previous studies established a model of disuse osteoporosis (DOP) with mechanical stress reduction in rats and found that no mechanical load can induce decreased expression of lncRNA H19 in bone tissue and lead to reduced bone formation and DOP through a Wnt signaling cascade." (PMID 34794451, 2021).